EGFR (epidermal growth factor receptor)
Diseases named in the same sentence as EGFR in open-access papers (continued):
Sharing a sentence is not in itself a finding about the gene and the disease.
non-small cell lung carcinoma (continued). "Osimertinib, a third-generation epidermal growth factor receptor (EGFR) tyrosine kinase inhibitor (TKI), has been approved for the treatment of metastatic EGFR T790M mutation-positive non-small cell lung cancer (NSCLC) patients who are resistant to TKI therapy." (PMID 37735252, 2023). "For example, epidermal growth factor receptor (EGFR) inhibitors, such as gefitinib (market brand name, Iressa) and erlotinib (brand name, Tarceva)—which were both approved for the treatment of non-small cell lung cancer—are prime examples of this mutation-driven kinase inhibitor modification." (PMID 37104389, 2023). "Similarly, in vitro studies, it was found that overexpression of PHLPP1 inhibited EGFR-TKI resistance in non-small cell lung cancer via the MAPK/ERK pathway." (PMID 37576883, 2023). "Examples of successful targeted therapies in cancer include, among many others, the small molecule inhibitors of the BRAF V600 oncogene in melanoma, and monoclonal antibodies against the Epidermal Growth Factor Receptor (EGFR) in non-small cell lung cancer (NSCLC)." (PMID 36975409, 2023). "Aberrant overexpression or activation of EGFR drives the development of non-small cell lung cancer (NSCLC) and acquired resistance to EGFR tyrosine kinase inhibitors (TKIs) by secondary EGFR mutations or c-MET amplification/activation remains as a major hurdle for NSCLC treatment." (PMID 37821451, 2023). "Whether patients with advanced non-small cell lung cancer (NSCLC) should choose an immune-combination therapy regimen after EGFR-tyrosine kinase inhibitors (EGFR-TKIs) resistance is currently unclear." (PMID 37907645, 2023). "Similarly, using single-cell data from an EGFR mutant non-small cell lung cancer (NSCLC) cell line treated with the EGFR inhibitor erlotinib, we predicted that 40% of cells were likely to exist in a G0 arrest state prior to treatment." (PMID 37221612, 2023). "Additionally, the same group presented a case of Non-Small Cell Lung Cancer that had EGFR T790M at a VAF of 3.5% that enrolled AZD9291 trial and achieved partial remission." (PMID 38259646, 2023). "Some studies have shown that EGFR mutations are a better prognostic predictor in cases of operable non-small cell lung cancer, while others have revealed no significant impact of EGFR mutations." (PMID 36766495, 2023). "Notably, the results of Phase II clinical trials for patients with non-small cell lung cancer indicated that a combination of simvastatin and the EGFR inhibitor gefitinib exerted better antitumor effects than treatment with the EGFR inhibitor alone." (PMID 37653037, 2023). "Platinum-based doublet chemotherapy was historically the standard first-line treatment for patients with recurrent or metastatic non-small cell lung cancer (NSCLC), whose tumors lack epidermal growth factor receptor mutations or anaplastic lymphoma kinase translocations." (PMID 36926505, 2023). "Intracranial activity is not limited to ALK-rearranged or EGFR-mutant non-small cell lung cancer." (PMID 38012621, 2023). "The combination of bevacizumab or ramucirumab with epidermal growth factor receptor-tyrosine kinase inhibitor (EGFR-TKI) therapy, chemotherapy, or immunotherapy for non-small-cell lung cancer (NSCLC) patients with EGFR mutations could have survival benefits." (PMID 36765600, 2023). "The Epidermal Growth Factor Receptor (EGFR) has previously been identified to be directly regulated by miR-218 in non-small cell lung cancer in vitro and in vivo and glioblastoma in vitro, and a subsequent study has been able to establish links to therapy resistance." (PMID 37088795, 2023). "The combination of anti-EGFR drugs with radiotherapy and chemotherapy has been widely used in the treatment of a variety of cancers, including nasopharyngeal cancer, colorectal cancer, and non-small cell lung cancer." (PMID 36814816, 2023).
non-small cell lung carcinoma (continued). "There were two cases of BRAF mutation other than V600E, comprising 0.5% of all non-small cell carcinoma, 0.8% of adenocarcinoma and non-small cell carcinoma without EGFR/ALK aberrations and 1.5% of adenocarcinoma without EGFR/ALK aberrations." (PMID 37374289, 2023). "The trial consisted of a total of 72 patients with HER2- or EGFR-positive solid tumors including BC (40%), non-small-cell lung cancer (NSCLC; 21%), ovarian cancer (8%), colorectal cancer (6%), glioblastoma (6%), renal cancer (4%), pancreatic cancer (3%), and other cancers (13%)." (PMID 37803271, 2023). "This drug delivery system demonstrated a synergistic effect with Erlotinib and sonodynamic treatment in three-dimensional tumor spheroids culture of non-small cell lung cancer cell lines through increasing the production of ROS and downregulating EGFR and HIF-1α." (PMID 37460927, 2023). "In non-small cell lung cancer (NSCLC), patients with low or moderate EGFR expression have shown better responses to EGFR inhibitors than those with high EGFR expression, emphasizing the role of EGFR mutation status in predicting drug sensitivity." (PMID 38275995, 2023). "The second study looked for an association between HMGB1 and EGFR mutations in a group including 280 patients with non-small cell lung cancer (NSCLC), some of whom were smokers and others who had never smoked." (PMID 37298365, 2023). "Here, we performed a meta-analysis to evaluate the efficacy of adjuvant EGFR-TKI versus non-EGFR-TKI treatment in patients with completely resected non-small cell lung cancer (NSCLC) harboring EGFR mutation." (PMID 36782320, 2023). "However, others reported that the over expression of FAM83B was negatively correlated with the survival in non-small cell lung carcinoma (NSCLC) patients and it was correlated with the activation of EGFR signal pathway and mutation of EGFR." (PMID 36690987, 2023). "Additionally, SLC25A1 inhibitor was synthetic lethal with the EGFR inhibitor AZD9291 in non-small cell lung cancer both in vitro and in animal models." (PMID 37981593, 2023). "Moreover, NK1R promotes non-small cell lung cancer progression through the transactivation of Epidermal Growth Factor Receptor (EGFR) and acts as a promising biomarker and therapeutic target in breast cancer." (PMID 36986466, 2023). "As ICIs have become an essential treatment modality in non-small cell lung cancer (NSCLC) treatment for those patients without EGFR or ALK mutations, it becomes necessary to develop reliable methods of predicting and monitoring immune responses to these drugs." (PMID 37638022, 2023). "EGFR amplification occurs in approximately 50% of patients with primary glioblastoma as compared to 8% of patients with secondary glioblastoma and 5% of patients with non-small-cell lung cancer." (PMID 38201434, 2023). "We confirmed the presence of EGFR wild type cell lines A549 in non-small cell lung cancer." (PMID 37508500, 2023). "EGFR (epidermal growth factor receptor) mutation is a major oncogenic driver in non-small cell lung carcinoma (NSCLC), and inhibition of EGFR signaling by EGFR-tyrosine kinase inhibitors (TKIs) represent the optimal clinical treatment strategy for NSCLC patients with EGFR mutations." (PMID 37760942, 2023). "In an earlier phase II trial, the combination onartuzumab-erlotinib (EGFR inhibitor) resulted in an improved overall survival in patients with non-small-cell lung cancer (NSCLC) who were cMET positive, defined as 50% of tumor cells staining with an IHC intensity of 2+/3+." (PMID 37046637, 2023). "A recently overall survival (OS) analysis from the AURA3 trial indicated that osimertinib improves median OS versus platinum-pemetrexed for patients with previously treated epidermal growth factor receptor (EGFR) T790M advanced non-small cell lung cancer (NSCLC)." (PMID 36324594, 2022).
non-small cell lung carcinoma (continued). "Increased expression of YPEL5, coding for a member of the carboxy-terminal to LisH (CTLH) complex, has been reported in erlotinib-treated EGFR-mutant non-small cell lung cancer, while recurrent YPEL5-PPP1CB fusion has been reported for chronic lymphocytic leukaemia." (PMID 36045381, 2022). "Targeted therapy against epidermal growth factor (EGFR) mutations has become the standard of care for non-small cell lung cancer, and there has not been an efficient genetic test for non-small cell lung cancer patients." (PMID 36230590, 2022). "Similarly, another CaCC inhibitor, diethylstilbestrol (DES), also inhibits ANO1 and ANO2, reduces EGFR activation, and decreases non-small cell lung cancer (NSCLC) cell migration." (PMID 36497413, 2022). "EGFR/PKC-δ/NF-κB pathway suppression in non-small-cell lung cancer." (PMID 35805019, 2022). "Over the past decades, systemic treatment strategies involving epidermal growth factor receptor (EGFR) tyrosine kinase inhibitors (TKIs) have greatly improved outcomes and represent the backbone of treatment for advanced EGFR-mutant non-small-cell lung cancer (NSCLC)." (PMID 35903676, 2022). "Several studies reported that high PD-L1 expression was associated with the presence of EGFR mutations in non-small cell lung cancer and was an independent negative prognostic factor for this disease." (PMID 35668455, 2022). "Interestingly, MET therapies have been shown to overcome anti-EGFR monotherapy and gemcitabine resistance in non-small cell lung cancer (NSCLC) and PDAC." (PMID 35804822, 2022). "In this case, we showed that the programmed cell death protein 1 (PD-1) inhibitor toripalimab plus chemotherapy and apatinib was effective and tolerable in a locally advanced EGFR-mutant non-small cell lung cancer (NSCLC) patient with a positive PD-L1 expression." (PMID 35898897, 2022). "Our results suggest a genuine role of the MEK5-ERK5 pathway in mediating EC proliferation, at least in epithelial EC cells that express EGFR, as it has been reported for other carcinoma cancers, such as hepatocellular carcinoma, prostate adenocarcinoma or non-small cell lung cancer." (PMID 36123565, 2022). "First, (IIA) the PD-L1 protein may be up-regulated after EGFR/RAS/MAPK pathway activation, either by over-expression of wild types of EGFR, such as in head and neck carcinoma, or by activating mutations of RAS and EGFR, which is more seen in non-small cell lung carcinoma (NSCLC)." (PMID 35628647, 2022). "Here, we attempted to identify targets that could be used to overcome resistance toward epidermal growth factor receptor (EGFR) tyrosine kinase inhibitors in non-small cell lung cancer (NSCLC)." (PMID 35565351, 2022). "ANGPTL4 may be an important regulator of EGFR-TKI resistance in patients with non-small-cell lung cancer." (PMID 36467503, 2022). "Resistance to EGFR inhibitors presents a major obstacle in treating non-small cell lung cancer." (PMID 35351890, 2022). "An intriguing development is an ErbB3-targeting antibody-drug conjugate, U3-1402, which has shown encouraging activity in ErbB3-overexpressing breast cancer and EGFR-mutant, EGFR inhibitor-resistant non-small cell lung cancer and would be of interest in combination with cetuximab in HNSCC." (PMID 35625959, 2022). "Although the use of epidermal growth factor receptor (EGFR) inhibitors in EGFR-mutant non-small-cell lung cancer (NSCLC) has led to a major clinical breakthrough, eventual resistance to these inhibitors limits their further clinical benefits as happened in conventional chemotherapy." (PMID 36309484, 2022). "CPNE1 was a target of miR-335–5 and CPNE1 silencing could effectively improve clinical responses of EGFR-tyrosine kinase inhibitors (TKIs) in non-small cell lung cancer." (PMID 35139863, 2022).
non-small cell lung carcinoma (continued). "For example, non-small cell lung cancer (NSCLC) with ALK (anaplastic lymphoma kinase) rearrangements showed a higher frequency of sclerotic bone lesions compared to NSCLC with EGFR-activating mutations, or NSCLC lacking either of these targetable alterations." (PMID 35159026, 2022). "The most encouraging thing is that, in recent years, studies have uncovered that natural polyphenols can inhibit the progress of tumors via a variety of mechanisms, for example, decreasing of PD-L1 expression through binding to EGFR in Non-small-cell lung cancer." (PMID 35875081, 2022). "Despite improvement in the overall survival of patients with non-small cell lung cancer (NSCLC) harboring epidermal growth factor receptor (EGFR) mutation, the effects of EGFR tyrosine kinase inhibitor (EGFR-TKI) treatment on bone metastasis remain unclear." (PMID 36581856, 2022). "EPAS1 may function as a link between stimulation of MET and T790M EGFR, indicating that this protein may be a potential treatment target, particularly in non-small cell lung cancers resistant to TKIs." (PMID 36313570, 2022). "Potential resistance mechanism to EGFR-TKI in non-small cell lung cancer–leptomeningeal metastases." (PMID 35978803, 2022). "A classic example of this is the EGFR gene in metastatic non-small cell lung cancer." (PMID 36388934, 2022). "Likewise, our group previously showed that miR-19b contributes to EGFR activation in non-small cell lung cancer (NSCLC) by targeting PPP2R5E." (PMID 36358647, 2022). "This third-generation EGFR TKI treats non-small cell lung cancers." (PMID 35743930, 2022). "For non-small cell lung carcinomas (NSCLC), especially adenocarcinomas, biomarker-guided therapies were successfully introduced into patient care about 17 years ago, mostly targeting activating EGFR mutations." (PMID 35565305, 2022). "Furthermore, gefitinib selectively inhibits EGFR and was first used to treat advanced non-small cell lung cancer after other treatments failed." (PMID 36158676, 2022). "Therefore, EGFR has become an important target for the treatment of cancer, including non-small cell lung cancer, head and neck cancer, breast cancer, glioma, cervical cancer, and bladder cancer." (PMID 35840984, 2022). "Somatic mutations which frequently occur in EGFR tyrosine kinase domain may predict response to EGFR tyrosine kinase inhibitors (TKIs) in patients with non-small cell lung cancer (NSCLC)." (PMID 35308511, 2022). "The current study aimed to investigate the function of the Hedgehog pathway and its association with epithelial-mesenchymal transition (EMT) in epidermal growth factor receptor (EGFR) tyrosine kinase inhibitor (TKI) resistance in non-small cell lung cancer (NSCLC)." (PMID 35154464, 2022). "As well, another report evinced that non-small-cell lung carcinoma (NSCLC) tumor overexpressing both EGFR and HER2 might exhibit higher sensitivity to EGFR tyrosine kinase inhibitor (TKI) compared to EGFR but not HER2 overexpressing tumors." (PMID 35093187, 2022). "An interesting finding of our study was that the rate of EGFR mutation was as high as 75.6%, which is almost twice that in patients with non-small cell lung cancer without another primary cancer." (PMID 36313724, 2022). "We aimed to explore the effect of EGFR amplification on EGFR mutation treatment-naive advanced non-squamous non-small cell lung cancer (NSCLC) patients." (PMID 36528578, 2022). "EGFR was an effective therapeutic target in non-small cell lung carcinoma." (PMID 35805016, 2022). "The US FDA has approved pembrolizumab as a single-agent first-line treatment for patients with stage III or metastatic non-small-cell lung cancer who have PD-L1 expression ≥1% and no EGFR or ALK mutations." (PMID 36411824, 2022).
non-small cell lung carcinoma (continued). "In the last few decades, several types of genetic mutations have been observed in non-small cell lung cancer (NSCLC), including genomic alterations in anaplastic lymphoma kinase (ALK), epidermal growth factor receptor (EGFR), ROS proto-oncogene 1 (ROS1) and rat sarcoma viral oncogene homolog (RAS)." (PMID 35517800, 2022). "Similarly, another important protein to be studied in the respect of hTid-1 is the Epidermal Growth Factor Receptor (EGFR) which is the major driver of Non-Small Cell Lung Cancer (NSCLC)." (PMID 35854300, 2022). "EGFR testing is a mandatory step before targeted therapy for non-small cell lung cancer patients." (PMID 35186727, 2022). "The identification of epidermal growth factor receptor (EGFR) mutations and development of EGFR tyrosine kinase inhibitors (EGFR-TKIs) have dramatically improved the prognosis of advanced EGFR-mutated non-small cell lung cancer (NSCLC), setting a landmark in precision oncology." (PMID 35626123, 2022). "The clinical features, survival outcomes and patterns of treatment failure of advanced non-small cell lung cancer (NSCLC) patients harboring distinct subtypes of EGFR mutations and receiving first-line EGFR tyrosine kinases inhibitor (TKIs) are not fully understood." (PMID 35189835, 2022). "Erlotinib, an inhibitor of the epidermal growth factor receptor widely used to treat unresectable non-small cell lung cancer, can improve the overall survival of patients with advanced pancreatic cancer by 0.33 months, but at the expense of greater adverse effects." (PMID 36143975, 2022). "The clinical significance of gene fusions detected by DNA-based next generation sequencing remains unclear as resistance mechanisms to EGFR tyrosine kinase inhibitors in EGFR mutant non-small cell lung cancer." (PMID 36153311, 2022). "Moreover, some groups have reported an indirect link between EGFR and PD-L1 expression via NF-κB in non-small cell lung cancer." (PMID 35668455, 2022). "Consequently, EGFR signaling overactivation has been detected in various malignant tumors, including non-small cell lung cancer (NSCLC), colon, head and neck, breast, and ovarian cancer." (PMID 35190588, 2022). "EGFR is reported to mediate intrinsic immunosuppression in tumors, and EGFR-targeted therapies are widely used for tumors such as colorectal cancer and non-small cell lung cancer." (PMID 36189267, 2022). "EGFR mutations were originally reported to affect the clinical outcomes of ICI treatment in TKI naïve, PD-L1-positive, and EGFR-mutant patients with advanced non-small-cell lung cancer." (PMID 35371031, 2022). "Among these eleven peptides, seven showed specific and selective binding and internalization into EGFR positive (EGFR+ve) cells, with two of them—P6 and P9—also demonstrating high specificity for non-small cell lung cancer (NSCLC) and glioblastoma cells, respectively." (PMID 35890400, 2022). "For example, EGFR (epidermal growth factor receptor) inhibitors were developed about twenty years ago and approved in Japan as molecular-targeted therapies for non-small-cell lung cancer (NSCLC); since then, a variety of EGFR inhibitors have been developed worldwide." (PMID 36551764, 2022). "Epidermal growth factor receptor (EGFR) signaling is a receptor tyrosine kinase (RTK) mediated signaling commonly upregulated in many different tumors such as non-small-cell lung cancer, metastatic colorectal cancer, glioblastoma, pancreatic cancer, and breast cancer." (PMID 35955440, 2022). "Approximately 3% to 10% of epidermal growth factor receptor (EGFR)-mutant non-small cell lung cancer (NSCLC) could transform to SCLC." (PMID 35223450, 2022). "The use of epidermal growth factor receptor (EGFR) tyrosine kinase inhibitor (TKI) is the first line treatment for EGFR-mutant advanced non-small cell lung cancer (NSCLC), but drug resistance will be acquired within 1-2 years, and the following treatment efficacy is poor." (PMID 36167460, 2022).